POLE (DNA polymerase epsilon, catalytic subunit)
Diseases named in the same sentence as POLE in open-access papers (continued):
Sharing a sentence is not in itself a finding about the gene and the disease.
cancer (continued). "This variant, like the other cancer-associated pathogenic POLE variants, is located in the exonuclease domain, which determines the proofreading activity of the polymerase." (PMID 36856825, 2023). "Addressing how POLE mutant cells can deal with loss of these genome stabilizing roles and what other mutations are associated with POLE tumors will help better understand the functions of the cancer mutations." (PMID 37388540, 2023). "As a consequence, POLE exonucleasic domain‐mutated tumors define a new hypermutated non MMR‐Deficient (MMR‐D) subtype of cancer." (PMID 35624529, 2022). "Together, these studies indicate that cancer patients with PolE mutations have good prognoses and favorable outcomes, in general." (PMID 35326618, 2022). "First, as expected, cancer types with higher mutational loads also included more subjects having mutations in DNA mismatch repair genes or POLE." (PMID 35053577, 2022). "In tumors, POLE mutations affecting the exonuclease domain result in a deficient DNA repair activity and a hyper/ultramutated cancer phenotype." (PMID 35624529, 2022). "Understanding the mechanisms of PolE mutations in cancer biology would provide insight to a causal relationship between genome instability and cancer progression." (PMID 35326618, 2022). "Recently, a pan-cancer study showed combining POLE and POLD1 mutation status into a simple model also can efficiently predict response to ICI therapy." (PMID 35344507, 2022). "In summary, cancer patients bearing PolE mutations display hypermutation and demonstrate good prognosis and a favorable outcome." (PMID 35326618, 2022). "An analysis of 1,278 patients with advanced cancer with low/moderate TMB treated with ICIs showed that the occurrence of POLE missense mutations outside the exonuclease domain was associated with better overall survival." (PMID 35780178, 2022). "An analysis of all cases in cbioportal.org and the ICGC data portal revealed 4 additional cancers (1 gastric cancer, 1 non–small cell lung cancer, 1 glioblastoma, and 1 colorectal cancer) that harbored the POLE V1368M mutation." (PMID 35274726, 2022). "Patients with POLE/POLD1 mutations harbored a markedly favorable prognosis in a pan‐cancer ICI cohort contained 1644 patients." (PMID 34862763, 2022). "Subsequent studies in a PolE-P286R mouse model confirm the pathogenicity of PolE mutation in cancer." (PMID 35326618, 2022). "Several phase 2 clinical trials (such as NCT03461952, NCT02693535, NCT03428802, and NCT03207347) are ongoing to evaluate the efficacy of ICIs or targeted therapies in patients with cancer and POLE/POLD1 mutations." (PMID 35189839, 2022). "Signature 14 is commonly found in cancers with ultra-high mutation rate and has been associated with concurrent MMRd and POLE mutations." (PMID 35012638, 2022). "Somatic or germline DNA Polymerase epsilon (PolE) mutations cause ultramutated (>100 mutations/Mb) cancer." (PMID 35326618, 2022). "We previously published a study investigating clinical and molecular profile of POLE‐mutated CRC cancers based on available public data." (PMID 35624529, 2022). "T‐1 had two different POLE mutations D319E and R821C, both documented in the Catalog of Somatic Mutations in Cancer database." (PMID 34351088, 2022). "Functional interrogation of the POLE V1368M mutation is needed to clarify its role in mediating the response of cancers to ICIs." (PMID 35274726, 2022). "Inactivating mutations in the POLE exo-domain are associated with an ultramutated phenotype attributed to error-prone replication and are observed in multiple cancer types including colorectal, endometrial, gastric, breast and brain cancers." (PMID 35274726, 2022). "These trials select CRC patients according to POLE mutations, which have been reported in colorectal and various cancers." (PMID 35328658, 2022). "15/51 (29%) male and 20/43 (46.5%) female POLE ED variant heterozygotes developed benign or malignant tumours of more than one site to the date of follow-up." (PMID 33948826, 2022).
cancer (continued). "Shcherbakova’s lab also characterized 13 other cancer-associated PolE mutations in the yeast model and found that only mutations that directly alter the exonuclease domain of the DNA binding cleft increase the mutation rate." (PMID 35326618, 2022). "POLE-associated cancers typically display hypermutation, and a unique mutational signature, with a predominance of C > A transversions in the context TCT and C > T transitions in the context TCG." (PMID 34228709, 2021). "Cancers harboring POLE mutations were also associated with elevated expression of several immune checkpoint genes and a favorable response to immunotherapy." (PMID 35095878, 2021). "In line with these considerations, data of the PORTEC-3 trial indicated that the combination of chemotherapy with radiotherapy showed no benefit compared to radiotherapy alone in adjuvant treatment of POLE-mutated cancer." (PMID 33467460, 2021). "A pan-cancer analysis of POLE/POLD1 mutations in 47,721 patients showed that 185/2586 esophagogastric cancer patients harbor such mutations." (PMID 33916348, 2021). "Another source of hypermutation in cancer is defective DNA polymerase proofreading due to mutations in polymerase ε (POLE) or polymerase δ (POLD1) genes." (PMID 33879792, 2021). "Patients with POLE/POLD1 mutations exhibited a significantly preferable prognosis in a multi-cancer-ICI cohort with 1644 patients." (PMID 34747716, 2021). "Temko and colleagues demonstrated that acquisition of POLE mutations induces a distinct pattern of mutations in cancer driver genes, a substantially increased mutation burden, and an enhanced immune response that is detectable even in precancerous lesions." (PMID 34034807, 2021). "Cancers with POLE exonuclease domain mutations show very high single-base substitution (SBS) mutation burdens whereas those with POLD1 exonuclease domain mutations show less elevated SBS burdens but are often associated with microsatellite instability." (PMID 34594041, 2021). "SBS10a, SBS10b and SBS28 were previously found in the subsets of colorectal, endometrial and other cancer types with somatically acquired POLE mutations." (PMID 34594041, 2021). "Extreme genomic instability is characteristic of tumors with POLE mutations, with the mutation burden being among the highest found in human cancers." (PMID 34150634, 2021). "Somatically acquired heterozygous missense mutations in the POLE or POLD1 exonuclease domains found in some human cancers cause defective proofreading and, consequently, high burdens of somatic mutations with distinctive mutational signatures." (PMID 34594041, 2021). "Currently, increasing research is focused on finding new markers for immunotherapy, and POLE gene mutations are considered a promising marker in various cancer types." (PMID 33125191, 2021). "We next wished to compare the mutation spectra occurring in POLE-P286R human cancers and the equivalent mutant in fission yeast." (PMID 34228709, 2021). "Recognizing the pathogenetic mutations of POLE is, therefore, necessary to classify a carcinoma as POLEmut." (PMID 34073635, 2021). "It is thought to be caused by neo-antigens that are generated as a result of the high mutation burden and render POLE mutant cancers responsive to immunotherapy." (PMID 32838755, 2020). "The resultant survival curves for these groups mirrored those seen in TCGA, with the highest risk of cancer-specific death (19%) in the copy number high group and lowest risk of cancer-specific death (2.6%) in the POLE group." (PMID 33256706, 2020). "By modeling human POLE cancer-associated mutations in its yeast ortholog, Pol2, we gained insights into native and cancer-associated Pol ε functions." (PMID 32415104, 2020).
cancer (continued). "It remains intriguing why the specific mutation spectrum varies even within cancer genomes with the same POLE mutation." (PMID 32012149, 2020). "This study refines our understanding of DNA polymerase fidelity and underscores genome-wide mutation spectrum and specific cancer driver mutation formation observed in POLE mutant cancers." (PMID 32012149, 2020). "In this study, we investigated genome-wide regional mutational profiles of different POLE mutants, as well as their influence on driver mutation formation in cancer." (PMID 32012149, 2020). "Cancer genomes with mutations in the exonuclease domain of Polymerase Epsilon (POLE) present with an extraordinarily high somatic mutation burden." (PMID 32012149, 2020). "We observed the greatest increase of nucleotide transversions in cancers with E/Q/Z mutations, consistent with the loss of POLE exonuclease activity in these tumors." (PMID 32838755, 2020). "Previous cancer genomics studies have identified a number of mutation hotspots in POLE, however how these different POLE mutants behave in affecting mutation distribution has not been studied." (PMID 32012149, 2020). "Mutations in the exonuclease domain of POLE, a DNA polymerase associated with DNA replication and repair, lead to cancers with ultra-high mutation rates." (PMID 32838755, 2020). "Functional POLE mutations have been identified in less than 1% of all cancer genomes but these genomes are characterized by exceptionally high tumor mutation burden." (PMID 32012149, 2020). "The analysis of thousands of cancers by The Cancer Genome Atlas (TCGA) consortium and academic institutions revealed a small group of cancers with mutations in POLE and an ultramutator phenotype." (PMID 32838755, 2020). "Two hereditary cancer families (2/2813; 0.07%) carried a pathogenic variant in POLE (p.Met294Arg), making a total of 5 carriers." (PMID 32792570, 2020). "Next, we determined the number of mutations in the exonuclease and polymerase domains of POLE in the 15 cancer types within our PANCAN compendium." (PMID 32838755, 2020). "Two cancer-associated changes in the exo domain of POLE deserve special attention, V411L, and L424V (rows 8 and 9)." (PMID 33255191, 2020). "To address the functions of POPS, we introduced mutations of conserved residues by modeling POLE changes found in cancer cells 22,23." (PMID 32415104, 2020). "Mutations can be found across the entire POLE gene, but those in the POLE exonuclease domain are most prevalent in cancers with ultra-high mutation rates (> 100 mut/Mb)." (PMID 32838755, 2020). "Another puzzle is why POLE mutations in the exo-coding part overwhelmingly outnumber POLD1 mutations in cancers if these pols both replicate the whole genome with comparable fidelity, but on different strands." (PMID 33255191, 2020). "POLE mutations have been found in various types of malignant neoplasms such as endometrial, colorectal, brain, stomach, breast, and pancreatic cancers." (PMID 32433714, 2020). "To address how perturbation of this region affects DNA replication, we modeled recurrent cancer-associated POLE mutations found there based on the following rationale." (PMID 32415104, 2020). "We and others have previously reported that C>T mutation load at CpG dinucleotides in many cancer types including POLE mutant cancers show strong positive correlation with 5-methylcytosine (5mC) level." (PMID 32012149, 2020). "Somatic mutations of POLE have been acknowledged in numerous cancers, resulting in the accumulation of DNA errors, leading to ultra-mutated tumors." (PMID 31864301, 2019).
cancer (continued). "Identifying error-prone variants of POLD1 and POLE and understanding the mechanisms that underlie their fidelity defects is, hence, also important in the context of cancer therapy." (PMID 31278166, 2019). "The colorectal (SNU-81 and HT-115) and endometrial (ESS-1) cancer cell lines with mutations in POLE continued to generate the associated base substitution signatures." (PMID 30849372, 2019). "A small group of pediatric GMBs contain the highest TMB reported in human cancer which result from germline biallelic mismatch repair defects and mutations in replicating DNA polymerase genes POLE or POLD1." (PMID 31604779, 2019). "Mutation-driven genomic instability occurs in POLE- or POLD1-mutated cancers, where the levels of mutational burden (based on SNVs) in POLE exonuclease domain mutated cancers are extremely high." (PMID 31747945, 2019). "An analysis of human cancer exomes revealed an increased prevalence of mutations in the POLE gene encoding Pol ε in a subset of colorectal and endometrial tumors with a very high mutation load." (PMID 30670696, 2019). "The trinucleotide context of this mutation (C[C>G]T) is not frequently observed in signature 10, supporting existing literature that demonstrates the POLE p.P286R mutation to underlie many instances of the presence of signature 10 in cancer." (PMID 30412573, 2018). "POLE mutations are common in patients with stage I, grade 3 cancers, who usually require adjuvant therapy." (PMID 30134578, 2018). "To estimate the impact of mutations generated by the POLE mutant on tumourigenesis, we analysed the substitution frequency of cancer-related genes." (PMID 29880869, 2018). "We show that the acquisition of POLE mutation causes a distinct pattern of mutations in cancer driver genes, a substantially increased mutation burden, and an enhanced immune response, detectable even in precancerous lesions." (PMID 29604063, 2018). "Using genome and exome sequencing, we found that multiple driver mutations in POLE‐mutant cancers show the characteristic POLE mutational signature, including those in genes conventionally regarded as initiators of tumourigenesis." (PMID 29604063, 2018). "Although it is clear that somatic POLE mutation causes a mutator phenotype 17 and acts as a cancer driver 4, 5, several questions about its contribution to tumourigenesis remain unanswered." (PMID 29604063, 2018). "Signature 10 arises in cancers which harbour Polymerase Epsilon (POLE) exonuclease domain mutations." (PMID 30412573, 2018). "An alternative cause of hypermutation in cancer is mutations in polymerases epsilon (POLE) and delta 1 (POLD1)." (PMID 30275357, 2018). "POLE is an essential gene, and nearly all variants reported in cancers are missense mutations, for which the pathogenicity cannot be definitively predicted in the absence of functional analyses." (PMID 29352080, 2018). "This is further underlined by recent case reports demonstrating the efficacy of anti-PD-1 inhibitors in advanced POLE-mutant or mismatch repair deficient cancers, including those of endometrial origin." (PMID 28344870, 2017). "Recent case reports provide proof of principle by demonstrating the efficacy of anti-PD-1 inhibitors in a limited number of advanced stage POLE-mutant or mismatch repair deficient cancers." (PMID 28344870, 2017). "First, it is unclear why hypermutated tumors with POLE exonuclease domain mutations have better survival than other tumors of the same cancer type." (PMID 28117753, 2017). "The median age at first cancer diagnosis was 40 years (range: 27–64 years) in 30 CRC patients carrying the POLE mutation and 32.5 years (range 23–57 years) in 13 CRC patients with POLD1 mutations." (PMID 27573199, 2017). "As expected, many statistically significant mutations occurred in mismatch repair genes, and POLE P286R, a genomic alteration that is known to cause hyper-mutant cancers, was the second most significant (p = 1.1 × 10–72)." (PMID 28420421, 2017).
cancer (continued). "Our findings indicate that a somatic POLE P286R mutation is a frequent carcinogenic driver in EOCRCs, leading to the rapid accumulation of additional somatic mutations, thus accelerating cancer development." (PMID 27612425, 2016). "A previous cancer genome study reported that POLE is significantly mutated in uterine cancer and this gene was specifically highlighted in a pan-cancer mutation signature analysis." (PMID 26519468, 2016). "We found that MSI-high CRCs and tumors harboring POLE exonuclease domain mutations were associated with a significantly higher neoantigen load when compared to MSS cancers." (PMID 27149842, 2016). "Sequencing of ultra-hypermutator cancers in children with germline mutations in the proofreading DNA polymerase epsilon (POLE) indeed found a maximum of ∼20 000 exonic mutations." (PMID 26949746, 2016). "This suggests that the same dominant mutational process is involved in cancer progression in this patient with POLE mutation." (PMID 25808843, 2015). "POLE-mutant tumors have a risk of recurrence approximately one third that of other ECs, and a relative risk of cancer death that appears even lower, though the latter finding was not statistically significant in our analysis." (PMID 25505230, 2015). "By exome sequencing we identified a novel mutation in POLE which seems to explain the cancer predisposition." (PMID 25860647, 2015). "The role of POLE in predisposition to cancer is consistent with previous studies where other mutations affecting the Polε exonuclease domain have been associated with CRC." (PMID 25860647, 2015). "We found POLE EDMs in about 7% of cancers, including some previously detected in CRCs and one mutation affecting the exonuclease active site." (PMID 24583393, 2014). "Using a panel of 75 cancer genes, POLE-mutated tumors exhibited an ~6-fold increase in mutations relative to non-POLE-mutated tumors, with a prevalence of G:C→T:A transversions, particularly at G:C base-pairs flanked 5' and 3' by an A:T base-pair." (PMID 24705290, 2014). "Since p.Pro286Arg mutant tumors show a much stronger bias towards transversions than cancers with p.Val411Leu, there is considerable evidence that specific POLE mutations have different effects on the somatic mutation spectrum." (PMID 24583393, 2014). "A particularly interesting issue is why germline POLE or POLD1 mutations can cause cancer, yet only POLE is somatically mutated." (PMID 23447401, 2013). "Subsequently, it was found that almost all of the hypermutant, MS-stable cancers had POLE exonuclease domain mutations (EDMs) 2,3." (PMID 23447401, 2013). "There exists a series of studies on the use of ICIs in cancer patients with POLE mutations." (PMID 40310397, 2025). "As expected, POLe is listed as a mutational cancer driver gene." (PMID 40806338, 2025). "Due to the widespread presence of POLE mutations across cancers, such approaches could also be further explored and validated in other cancer diseases." (PMID 39931062, 2025). "For upper gastrointestinal tract evaluation, periodic upper endoscopy every 1–3 years may be appropriate, especially in patients with POLE mutations, given reports of duodenal adenomas and carcinomas in this population." (PMID 40741356, 2025). "Current data suggest that carcinomas classified within the POLE-mutated subgroup may derive significant benefit from the de-escalation of postoperative adjuvant therapy, given their consistently favorable outcomes." (PMID 40217749, 2025). "Extra‐colonic manifestations have been reported to vary depending on the affected gene: POLE‐related PPAP is associated with duodenal adenomas or carcinomas and brain abscesses, while POLD1‐related PPAP has been linked to endometrial cancer, breast cancer, and brain tumors." (PMID 40741356, 2025). "Generally, there are much less cancer driver mutations in POLD1 than in POLE in human cancers." (PMID 37891003, 2024). "Conversely, SBS10 is the canonical signature of POLE deficiency in MMRp cancers." (PMID 39390083, 2024).